ISG15 (ISG15 ubiquitin like modifier)
Diseases named in the same sentence as ISG15 in open-access papers (continued):
Sharing a sentence is not in itself a finding about the gene and the disease.
autoimmune disease (7 papers, 2020 to 2025). A disorder resulting from loss of function or tissue destruction of an organ or multiple organs, arising from humoral or cellular immune responses of the individual to their own tissue constituents. "Humans deficient in USP18 or ISG15 develop severe autoimmune disease due to uncontrolled IFN-I signaling." (PMID 39969510, 2025). "Among ISGs, both ddx58 with IFIT1 and ISG15 with OAS1 showed significant positive correlations in all types of autoimmune disease and HC samples." (PMID 34848794, 2021). "Thus, we propose ISG15 in NETs as a new component in the physiopathogenic scheme of autoimmune diseases such as SLE, with an effector correlate that includes the induction of Th1 lymphocytes with a proinflammatory potential (Proposed hypothetic model)." (PMID 33176801, 2020). "Thus, we tested whether ISG15 played this role also in those autoimmune diseases where type I IFNs are produced endogenously and contribute to immunopathogenesis, such as SLE." (PMID 33376595, 2020). "Strikingly, the ISG15 gene was recently found upregulated in whole blood from SLE, a typical T1-T17 autoimmune disease, and its levels decrease after treatment." (PMID 39409176, 2024). "For example, USP18 and ISG15 are negative feedback regulators of IFNAR-JAK-STAT signaling, and their deficiency in humans drives severe autoimmune disease." (PMID 39969510, 2025). "Additionally, we predicted and verified the STAT1 as the possible TF of the ISG15 and CD53 in the two autoimmune diseases." (PMID 39136821, 2024).
glioblastoma (7 papers, 2022 to 2025). The most malignant astrocytic tumor (WHO grade IV). "For instance, glioblastoma displays high levels of ISG15, which are associated with poor survival." (PMID 37711589, 2023). "Conversely, ISG15 showed a protective anti-tumour role in glioblastoma and ovarian models." (PMID 35864381, 2022). "ISG15 upregulation also seems important for the ISGylation of essential proteins, such as OCT4, and the cell stemness of glioblastoma cells." (PMID 37711589, 2023). "When previously explored in multiple glioblastoma cell lines, pIC was shown to modestly induce IFNβ expression but significantly induced ISG (ISG15 and CXCL10) expression in some of these cultures." (PMID 35603190, 2022).
glioma (7 papers, 2005 to 2025). A benign or malignant brain and spinal cord tumor that arises from glial cells (astrocytes, oligodendrocytes, ependymal cells). "The five glioma subpopulations were as follows: C0 CHCHD2P9+ glioma cells (2,821 cells), C1 MALT1+ glioma cells (2,124 cells), C2 MT1G+ glioma cells (1,614 cells), C3 SOX4+ glioma cells (1,575 cells), and C4 ISG15+ glioma cells (128 cells)." (PMID 40630954, 2025).
hepatitis C (7 papers, 2011 to 2023). "For example, ISG15 is a well-known factor that is associated with IFN resistance in hepatitis C patients, and was highly induced in HEV-infected cells as well as in HEV-infected patients and chimpanzees." (PMID 28558073, 2017). "Surprisingly though, a recent study even showed that ISG15 is favorable of hepatitis C virus infection." (PMID 21992229, 2011). "ILK increases the hepatitis C virus infection by inhibiting IFN-α-induced PKR activation and ISG15 expression." (PMID 35350437, 2022).
Immunodeficiency (7 papers, 2017 to 2023). Failure of the immune system to protect the body adequately from infection, due to the absence or insufficiency of some component process or substance. "The upregulated ISG15 can activate immune cells and induce an inflammation response, causing immune dysfunction in patients with pSS." (PMID 36465909, 2022). "No ocular features of ISG15-associated immunodeficiency have been described, and ISG15-deficient mice do not appear to exhibit a neuroinflammatory phenotype." (PMID 34258050, 2021). "According to the OMIM (Online Mendelian Inheritance in Man) database, ISG15, IRF9, and STAT1 are related to immunodeficiency." (PMID 38113079, 2023).
psoriasis (7 papers, 2013 to 2025). An autoimmune condition characterized by red, well-delineated plaques with silvery scales that are usually on the extensor surfaces and scalp. "IVL, OASL, and ISG15 were also the potential gene targets of the drugs for treating psoriasis in this study." (PMID 32669126, 2020). "In psoriasis lesions, ISG15 mRNA is elevated 4-fold and prior work has confirmed that ISG15 protein is widely distributed in the psoriatic dermis and epidermis." (PMID 24260178, 2013). "Another study showed that psoriasis was associated with the overexpression of antiviral genes (such as ISG15 and TRIM22) in the skin, but not in the blood." (PMID 35609018, 2022). "Finally, PPI network analysis demonstrated that CXCL10 was the hub gene with the highest degree, and CXCR2, CXCL10, IVL, OASL, and ISG15 were the potential gene targets of the drugs for treating psoriasis." (PMID 32669126, 2020). "ISG15 has several functions that are not fully understood, but increased ISG15 in psoriasis lesions may amplify or sustain inflammation responses in two ways." (PMID 24260178, 2013). "ISG15, MX1, IFI44L, and IFI27 were the characteristic genes of psoriasis in suprabasal keratinocytes." (PMID 36172384, 2022). "ISG15, MX1, IFI44L, and IFI27 were the characteristic psoriasis genes found in suprabasal keratinocytes." (PMID 36172384, 2022). "Previous studies revealed that the cell cycle encounters interruption during the G1/S transition phase if ISG15 was absent in a psoriasis cell model, thereby reducing the proliferation of keratinocyte cells responsible for epidermal formation." (PMID 40560938, 2025). "In addition, 8 genes (DEFB103A, OASL, HERC6, ISG15, MKI67, MX1, MXD1, SCO2) were considered to have statistically significant differences in sensitivity of short-term treatment for psoriasis." (PMID 40560938, 2025). "Of the most psoriasis-specific DEGPs, the majority were induced by IL-17A (e.g., FERMT1, GLUL, SULT2B1); in contrast, the most non-specific DEGPs were not disproportionately induced by IL-17A and several were repressed (e.g., AKR1B10, RNF213, ISG15)." (PMID 26251673, 2015). "Besides, some psoriasis-related genes such as SPRR genes, HSD11B1, GGH, CXCR2, IVL, OASL, ISG15, and CXCL10 may be important targets in psoriatic therapy." (PMID 32669126, 2020).
co-infection (6 papers, 2020 to 2025). "Thus, to investigate the capacity of ISG15 variants to enhance innate responses, we performed in vitro co-infection assays using iBMDMs and recombinant MVA vectors encoding antigens from relevant viral pathogens." (PMID 40733673, 2025). "The co-expression of RSAD2 and ISG15 during co-infection suggests a coordinated IFN-mediated immune response in the caudal fin." (PMID 40943072, 2025). "More importantly, all of the tested cytokines and chemokines, except for ISG15, were elevated in co-infection with H5N1 compared with the levels induced by SCoV2/D614G single infection." (PMID 40431161, 2025). "The IFN-λs, IL-8, IP-10, and ISG15 expressions were reduced by co-infection when compared with H5N1 single infection." (PMID 40431161, 2025). "The relative transcription levels of ISGs showed that except for Mx, the transcription levels of OAS, PKR, ZAP and ISG15 in co-infection or post-infection groups were higher than those in pre-infection group." (PMID 35337040, 2022). "Notably, co-infection of ISG15 with MVA-ZIKV and MVA-SARS-CoV-2 vaccine candidates enhanced the magnitude of antigen-specific immune responses in both vaccine models." (PMID 40733673, 2025). "However, we found that H5N1 co-infection induced the highest level of ISG15, which may be the reason for the observed slight reduction in SCoV2 replication." (PMID 40431161, 2025). "In the caudal fin, Mc+ (1 day after co-infection with T. bryosalomne) fish showed mild immune activation with C4B upregulation, while Tb+ fish exhibited a stronger response involving IFI44, ISG15, RSAD2, and TLR7 signaling." (PMID 40943072, 2025). "There was an elevated trend in IFN-λ1, IL-6, ISG15, and MCP-1 expression with H3N2 (4550) infection, which were suppressed upon co-infection with SCoV2/BA." (PMID 40431161, 2025). "It is thought that in patients with HBV/HCV co-infection, HBV replication is strongly suppressed by HCV-induced upregulation of ISGs, including ISG15 and ISG56." (PMID 31969598, 2020). "Furthermore, co-infection with H1N1 or H3N2 (OK/483) enhanced the induction of IFNs, IP-10, ISG15, MDA-5 when compared with SCoV2/BA.1 single infection." (PMID 40431161, 2025). "Co-infection of SCoV2 with H3N2 (OK/483) led to enhanced levels of IFNs, IP-10, ISG15, and MDA5 than that by SCoV2 infection while H1N1 co-infection enhanced IP-10, ISG15, and MDA5 compared with SCoV2 single infection." (PMID 40431161, 2025). "MVA-B served as a control vector, as previous in vitro studies have demonstrated that co-infection of ISG15, in both GG and AA forms, does not interfere with antigen expression from this construct." (PMID 40733673, 2025). "Our results showed that IFN1, Mx-1, ISG15, and VIG1 are significantly elevated in co-infection, which indicated that IHNV and IPNV co-infection could induce stronger antiviral responses." (PMID 36016354, 2022). "Moreover, in vitro co-infection of macrophages with MVA-based vaccine vectors and the ISG15AA mutant led to a marked increase in proinflammatory cytokine production, highlighting a dominant role for the extracellular, ISGylation-independent functions of ISG15 in shaping vaccine-induced immunity." (PMID 40733673, 2025).
colitis (6 papers, 2017 to 2025). Inflammation of the colon. "In the bowel samples from patients with ICI‐induced colitis, the expression of ISG15 is also significantly increased in mucosa, indicating that IFN‐γ triggers inflammation by macrophages." (PMID 39934971, 2025). "It was shown that ISG15 was up‐regulated in the mucosa of patients with ICI‐induced colitis." (PMID 39934971, 2025). "Notably, we observed a population of Tregs with high expression of ISGs (e.g., Irf7, Irf9, Isg15) from mesenteric lymph nodes (MLNs) during dinitrobenzenesulfonic acid (DNBS)–induced colitis." (PMID 38085267, 2024). "The mRNA expression of ISG15 was found to be increased in patients with active IBD and experimental rats with colitis, and ISG15 could enhance the IL-12-induced release of IFN-γ." (PMID 37554552, 2023). "TSG-6 has been described as an anti-inflammatory mediator with therapeutic potential in colitis, whereas DDIT4 and ISG15 are stress- and inflammation-related factors." (PMID 41354832, 2025). "After induction of acute colitis with DSS, we found with EdgeR and CuffDiff2 analyses that the expression of 11 genes (Clps, Ddx60, Fgb, Fgg, Ifi44, Ifit2, Isg15, Itih3, Itih4, Oas3 and Usp18), which are involved in antimicrobial response, was increased in MMP-9−/− compared to WT mice." (PMID 28561062, 2017).
esophageal squamous cell carcinoma (6 papers, 2016 to 2023). Esophageal squamous cell carcinoma (ESCC) is a type of esophageal carcinoma (EC) that can affect any part of the esophagus, but is usually located in the upper or middle third. "For example, the expression of ISG15 has been demonstrated to be elevated in esophageal squamous cell carcinoma (ESCC) and to be closely associated with clinical outcome, indicating that ISG15 may be used as a prognostic biomarker in ESCC patients." (PMID 36771004, 2023). "ISG15, via the c-MET/Fyn/beta-catenin pathway in esophageal squamous cell carcinoma, shows tumor-promoting effects." (PMID 33123466, 2020).
Hypertension (6 papers, 2023 to 2026). The presence of chronic increased pressure in the systemic arterial system. "The ISG15 pathway has been identified as a novel mediator of hypertension-associated vascular damage, contributing to endothelial dysfunction, vascular remodelling, and increased oxidative stress." (PMID 41496209, 2026). "ISG15-deficient mice are protected from angiotensin II–induced hypertension and vascular damage, whereas excessive ISGylation exacerbates fibrosis, inflammation, and aortic rupture." (PMID 41496209, 2026). "One of the IFN‐regulated proteins upregulated by both eNOS and ADAR1 knockdown in human endothelial cells IFN‐stimulated gene 15 (ISG15); which plays an essential role as host‐defence response to microbial infection, was identified as a possible mediator of hypertension‐associated vascular damage." (PMID 40150952, 2025). "Moreover, mice deficient in Isg15 were protected against angiotensin II‐induced hypertension and vascular dysfunction, and ISG15 was one of the IFN‐regulated proteins upregulated by both eNOS and ADAR1 knockdown in human endothelial cells." (PMID 40150952, 2025). "Aging is associated with both hypertension and ISG15 activation." (PMID 37025175, 2023). "Moreover, Isg15-null mice were found to be protected against angiotensin II-induced hypertension, elastin remodeling, vascular stiffness, endothelial dysfunction, and expression of inflammatory and oxidative stress markers." (PMID 37025175, 2023).
myocarditis (6 papers, 2023 to 2025). Myocarditis is a condition that is characterized by inflammation of the heart muscle (myocardium). "ISG15 activation is associated with coxsackievirus B3-induced myocarditis in mice, and cardiomyocyte ISG15 expression contributes significantly to the suppression of viral replication." (PMID 37025175, 2023). "We found M2 macrophages increased in DM and myocarditis compared to the healthy control, associating with the expression of IFIT3, OAS3, ISG15, and RSAD2 in DM and myocarditis positively." (PMID 37118825, 2023). "The expression levels of IFIT3, OAS3, ISG15, and RSAD2 were verified in myocardial tissue between myocarditis mice and normal control." (PMID 37118825, 2023). "We finally identified 4 common hub-genes related to the immune process of myocarditis and DM: IFIT3, OAS3, ISG15, and RSAD2." (PMID 37118825, 2023). "ISG15 in the cardiomyocytes contributes to the suppression of viral replication, and the absence of protein modification with ISG15 was accompanied by profound exacerbation of myocarditis in mice infected with coxsackievirus B349." (PMID 38049441, 2023).
esophageal cancer (5 papers, 2017 to 2025). A primary or metastatic malignant neoplasm involving the esophagus. "Here, with endogenous expression in esophageal cancer cells, we report the opposite effect; knockdown of ISG15 or UBE2L6 promotes autophagy." (PMID 28186990, 2017). "In addition, knockdown of ISG15 or UBE2L6 in chemotherapy-sensitive esophageal cancer (ECA) cells enhances autophagy, and only ISG15 knockout enhances both autophagy and chemotherapy-induced cell survival." (PMID 41193953, 2025). "Reportedly, ISG15 and UBE2L6 were identified as negative regulators of autophagy in esophageal cancer cells." (PMID 31309113, 2019). "In this study, we have identified ISG15 and UBE2L6 as negative regulators of autophagy in esophageal cancer cells." (PMID 28186990, 2017).
Flavivirus Infections (5 papers, 2011 to 2024). Infections with viruses of the genus FLAVIVIRUS, family FLAVIVIRIDAE. "As the expression of ISG15 enhances the effects of the ESCRT protein depletion during flavivirus infection and TSG101 can be targeted by ISG15 during IAV infection, we investigated the effects of ISG15 on the ESCRT proteins during flavivirus infection." (PMID 34851141, 2022). "Little work has been done on the physiological relevancies of ISG15 to flavivirus infections." (PMID 21992229, 2011). "Here we provide mechanistic insight of the arms race between ISG15, USP18 and NS5 which suggests that protein/protein dynamics adjacent to IFNAR are a key determinant for the outcome of flavivirus infection." (PMID 38384473, 2024). "According to a previous study involving flavivirus infection, the mRNA levels of six key ISGs, i.e., IFITM1, IFITM3, OASL2, PKR, VIPERIN, and ISG15, were analyzed by real-time PCR in the spleen and liver." (PMID 35310394, 2021).
heart failure (5 papers, 2020 to 2024). Inability of the heart to pump blood at an adequate rate to meet tissue metabolic requirements. "More recently, experimental findings have shown that ISG15 deficiency preserves cardiac function in mice under pressure overload, suggesting that protein ISGylation is an inflammation-induced post-translational modification that may contribute to heart failure development." (PMID 38049441, 2023). "ISG15 is inducible in mouse and human cardiomyocytes and is upregulated in human heart failure." (PMID 37115698, 2023). "To determine whether ISG15 upregulation also occurs in human heart failure, we first explored previously published bioinformatic data." (PMID 37115698, 2023). "ISG15 has been shown to defend against heart failure in virus-induced cardiomyopathy." (PMID 32457708, 2020). "Thus, ISG15 induction and protein ISGylation are intracellular mechanisms that provide a mechanistic link between sterile inflammation, adverse ventricular remodeling, and eventual heart failure development." (PMID 37115698, 2023). "In sum, ISG15 upregulation is a feature of pathological ventricular remodeling, and protein ISGylation is an inflammation-induced posttranslational modification that may contribute to heart failure development by altering cardiomyocyte protein turnover." (PMID 37115698, 2023). "However, the expression of ISG15 pathway components and several inflammatory cytokines is upregulated by cardiomyocyte-specific IkB kinase/NFκB activation, leading to cardiomyopathy and heart failure." (PMID 37025175, 2023).
lymphoma (5 papers, 2016 to 2026). A malignant (clonal) proliferation of B- lymphocytes or T- lymphocytes which involves the lymph nodes, bone marrow and/or extranodal sites. "The RNA-seq data revealed that Δ3C-induced tumors have a greatly increased type I interferon response compared to the wild-type virus-infected lymphomas, and this effect was confirmed by both qPCR analysis of tumor cDNA, and by ISG15 IHC staining." (PMID 30125329, 2018). "Whereas NDV infected different lymphoma subtypes with variable efficiency, it induced robust expression of IFN-stimulated genes (STAT1, MX1, ISG15) across all patient samples." (PMID 36418317, 2022). "Moreover, they observed that the levels of ISG-15 in labial minor salivary gland tissues are correlated with its levels in peripheral blood and extended the idea that ISG-15 may serve as a potential biomarker for Sjögren-related lymphoma development." (PMID 38790257, 2024).
oral squamous cell carcinoma (5 papers, 2020 to 2022). "Interferon stimulated gene 15 (ISG15) inhibits HIV-1 replication, while miR-138 inhibits the expression of ISG15 in oral squamous cell carcinoma (OSCC) cells." (PMID 36685589, 2022). "The first one to be recognized was ISG15 and has been described in many tumor biopsies from several cancers including oral squamous cell carcinoma." (PMID 32670885, 2020). "The objectives were to evaluate the expression of Ki-67, Cornulin and ISG15 in non-involved mucosal surgical margins and the association of clinicopathological prognosticators with local relapse in oral squamous cell carcinoma." (PMID 34941961, 2021). "For example, induction of ISG15 or IFIT1 in human squamous cell carcinoma cancer cell line conferred doxorubicin chemo-resistance, or overexpression of IFIT1 and IFIT3 in oral squamous cell carcinoma (OSCC) promoted experimental metastasis." (PMID 35565392, 2022).